MTOR (mechanistic target of rapamycin kinase)
Diseases named in the same sentence as MTOR in open-access papers (continued):
Sharing a sentence is not in itself a finding about the gene and the disease.
teratoma (2 papers, 2017 to 2018). A non-seminomatous germ cell tumor characterized by the presence of various tissues which correspond to the different germinal layers (endoderm, mesoderm, and ectoderm). "Depletion of IGF-I or IGF-II in the stem cells used for teratoma assays caused a decrease of mTOR and MMP activation in the adjacent tissue and triggered a smaller proportion of murine cells in the teratomas." (PMID 28928383, 2017). "Samples with teratoma components had high pathway activities for the mammalian target of rapamycin (mTOR) and myogenesis, which is consistent with their differentiated nature." (PMID 29898407, 2018). "Adjacent to the teratoma, induction of invasiveness becomes detectable, accompanied by the activation of both, mTOR and MMPs." (PMID 28928383, 2017). "Furthermore, we performed in vivo experiments demonstrating that the application of human pluripotent stem cells and teratoma formation trigger induction of the mTOR pathway and activation of MMPs in mouse cells in the muscle tissue adjacent to the teratoma." (PMID 28928383, 2017).
thoracic cancer (2 papers, 2019). A primary or metastatic malignant neoplasm affecting the tissues of the thorax. "It stands to reason that YB-1 overexpression is likely to be, at least in part, linked to the prominent role mTOR signaling plays in thoracic cancers." (PMID 31632972, 2019). "In order to evaluate the potential effects of disruption of circadian clock in thoracic cancer patients, we attempted to compute the activities of hallmark pathways including TSC/mTOR, RTK, RAS/MAPK, PI3K/AKT, Hormone ER, Hormone AR, EMT, DNA Damage Response, Cell Cycle, and Apoptosis pathways." (PMID 31881010, 2019). "Fisetin was also found to inhibit mTOR and PI3K/Akt signaling in NSCLC cells, both of which are important in both thoracic cancer biology and YB-1 regulation (see section “Translational Regulation of YB-1”)." (PMID 31632972, 2019).
toxoplasmosis (2 papers, 2024 to 2025). A parasitic disease contracted by the ingestion or fetal transmission of toxoplasma gondii. "By focusing on host metabolic regulation via PI3K/Akt/mTOR, this work advances understanding of parasitism and proposes host-directed therapies to disrupt parasite proliferation by modulating the metabolic microenvironment, highlighting its therapeutic potential against toxoplasmosis." (PMID 41427835, 2025).
type 1 diabetic nephropathy (2 papers, 2021). "For instance, phosphorylated/activated forms of AKT (Thr308) and mTOR (Ser2448) were suppressed by losartan in type 1 diabetic nephropathy." (PMID 34238205, 2021). "Several studies have shown that the activation of the PI3K/AKT/mTOR pathway is involved in the autophagy of glomerular mesangial cells, which exhibited increased phosphorylation of mTOR, PI3K, Akt, and mTOR STZ-induced type 1 diabetic nephropathy (T1DN)." (PMID 34957109, 2021).
upper respiratory tract infections (2 papers, 2018 to 2019). "In contrast, patients who did and did not receive mTOR inhibitors experienced similar adverse events, such as upper respiratory tract infections (RR = 1.08, 95% CI = 0.81,1.45, P = 0.59) and nasopharyngitis (RR = 0.86, 95% CI = 0.60,1.21, P = 0.38)." (PMID 30760308, 2019).
urinary system cancer (2 papers, 2017 to 2022). "In this meta-analysis of Asian population, the carriers of mTOR rs2295080 TG, GG genotype and GG/TG genotypes showed a significantly decreased the risk of overall cancer, the urinary system cancer and digestive system cancer." (PMID 29259266, 2017). "We found that mTOR rs2295080 TG, GG genotype and GG/TG genotype carriers showed an decreased in the overall cancer risk, urinary system cancer and digestive system cancer, nevertheless TT genotype of rs2295080 was associated with increased the risk of blood system cancer." (PMID 29259266, 2017). "Immunohistochemical staining (IHS) and GSEA analysis were used to investigate the expression of mTOR in urinary system cancer." (PMID 35082928, 2022). "In silico tools and immunohistochemical staining (IHS) analysis were used to investigate the expression of mTOR in three main urinary system cancers." (PMID 35082928, 2022). "The heterogeneity of mTOR rs2295080 was also present in the subgroup of urinary system cancer and digestive system cancer under the dominant model." (PMID 29259266, 2017).
urinary system tumors (2 papers, 2020 to 2021). "We reached similar negative conclusions regarding the association between mTOR rs2536 and cancer risk in the overall population and in the subgroup of studies on “urinary system tumors” or “digestive system tumors”." (PMID 32597485, 2020). "Considering the high sensitivity of urinary tract tumors to programmed cell death including ferroptosis, we believe that combination of ferroptosis-inducer with ATP-competitive mTOR kinase (such as PP242) or dual mTOR/PI3K (such as NVP-BEZ235) may be a new strategy for treating RCC." (PMID 35082669, 2021).
uterine tumor (2 papers, 2023 to 2025). "The PI3K/AKT/mTOR signaling pathway plays a critical role in uterine tumor biology, with immunohistochemical analyses demonstrating that nuclear phosphorylated Akt and mTOR expression levels increase progressively from benign ULM to intermediate STUMP to malignant ULMS." (PMID 40867239, 2025).
vasculitis (2 papers, 2020 to 2024). "mTOR activity may represent a common denominator driving cellular activity of diverse pathogenic population and as such represent a unifying target to treat vasculitis." (PMID 33717054, 2020). "mTOR signalling pathway orchestrates the formation of the SMC-derived luminal myofibroblasts that drive arterial stenosis in vasculitis." (PMID 39271773, 2024). "In view of these findings in a murine model of vasculitis, we were keen to examine if the mTOR pathway is also activated in the luminal myofibroblasts that emerge in human vasculitis." (PMID 39271773, 2024). "We and others have reported that the mechanistic target of the rapamycin (mTOR) pathway becomes activated by multiple populations during vasculitis." (PMID 39271773, 2024). "mTOR is a critical signaling hub in all cell types relevant for vasculitis, including T cells, which rely on mTOR activity for their development, differentiation functional fitness." (PMID 33717054, 2020). "Thus, mTOR is an intrinsic and essential regulator of luminal myofibroblast formation that is activated in vasculitis patients and therapeutically tractable." (PMID 39271773, 2024). "Collectively, these findings illustrate that mTORC1 signalling is an intrinsic and essential process for the development of SMC-derived luminal myofibroblasts and that attenuating luminal myofibroblast formation (via targeting mTOR) reduces arterial stenosis in vasculitis." (PMID 39271773, 2024). "Our findings also raise the question of which factors trigger mTOR activation during vasculitis?" (PMID 39271773, 2024). "To address whether mTOR signalling directly controls the development of luminal myofibroblasts during vasculitis, we asked whether removing mTOR signalling from SMCs abrogated their development?" (PMID 39271773, 2024). "Hence, we suggest that mTOR is an intrinsic, essential and druggable pathway which is activated in the luminal myofibroblasts that drive adverse blood vessel remodelling in vasculitis patients." (PMID 39271773, 2024). "We next investigated whether the luminal myofibroblasts that emerge in other forms of vasculitis also activate the mTOR signalling pathway." (PMID 39271773, 2024). "Thus, Myh11-derived cells in both layers of the vessel activate mTOR signalling during vasculitis." (PMID 39271773, 2024). "For these experiments, we treated murine aortic SMCs with cytokines (with or without the mTOR inhibitor rapamycin) and stained for phospho-S6 and SAA3, a cytokine we found to be highly expressed by activated SMCs during CAWS-induced vasculitis." (PMID 39271773, 2024).
von Hippel-Lindau disease (2 papers, 2018 to 2023). An autosomal dominant disorder caused by pathogenic variants in the VHL gene, leading to an increased risk of various benign and malignant tumors, including hemangioblastomas, retinal hemangiomas, endolymphatic sac tumors, renal cell carcinoma, and pheochromocytomas. "There is evidence that mTOR inhibitors should be the favored immunosuppressant in patients with loss of VHL function and has been used in transplantation of patients with Von Hippel Lindau disease." (PMID 30326848, 2018).
Werner syndrome (2 papers, 2017 to 2023). "CTH was decreased in fibroblasts from patients with Werner syndrome, leading to an excess activation of the mammalian target of rapamycin (mTOR)." (PMID 28275217, 2017). "There is no known treatmentIs under study: mTOR inhibitors, selective inhibitors of p38 mitogen-activated protein kinase, hiPSCs derived from fibroblasts from Werner syndrome patients, human embryonic stem cell therapy." (PMID 37600771, 2023).
acral melanomas (1 paper, 2021).
acute megakaryocytic leukaemia (1 paper, 2019). "The Runx1 target, Pik3cd, is a member of the mTOR pathway and directly regulated by Runx1 in acute megakaryocytic leukaemia cells." (PMID 31395869, 2019).
adenovirus-infection (1 paper, 2018). "Moreover, the expression of E4 induced by E1A via cellular transcription factor E4F, participates in the activation of the PI3K/mTOR pathway and play an important role in adenovirus-infection." (PMID 29896171, 2018).
adrenal adenoma (1 paper, 2025). "The concurrent diagnosis of a KRAS-driven PRNRP and a TSC/mTOR pathway-associated RCC-FMS, accompanied by an adrenal adenoma, forms a distinctive clinical scenario." (PMID 41367859, 2025).
adrenal cancers (1 paper, 2020). A carcinoma involving a adrenal gland. "Overexpression of (P) RR, which may contribute to cancer initiation and progression via the Wnt/β-catenin, RAS, MAPK/ERK and PI3K/AKT/mTOR pathways as well as V-ATPase function, has been observed in various cancers including pancreatic, brain, colorectal, endometrial, breast and adrenal cancers." (PMID 32143717, 2020).
alcohol-related disorders (1 paper, 2022). Disorders related to or resulting from abuse or mis-use of alcohol. "While the role of the mTOR network in cocaine- and alcohol-related disorders is well established, little is known about its participation in opiate use disorders." (PMID 35467104, 2022).
amenorrhea (1 paper, 2016). The absence of menses in a woman who has achieved reproductive age. "While some data indicate that mTOR inhibition may partly be associated with the control of puberty onset, it has also been suggested that amenorrhea could be caused by TSC per se and may not be related to the treatment with mTOR inhibitors." (PMID 27502586, 2016).
ampullary cancer (1 paper, 2012). "The presence of a deletion in PTEN in this ampullary cancer would be predicted to release from inhibition activation of the PI3K/mTOR pathway." (PMID 22762308, 2012).
ankylosing spondylitis (1 paper, 2024). An autoimmune chronic inflammatory disorder characterized by inflammation in the vertebral joints of the spine and sacroiliac joints. "Additionally, STAT3 has been shown to promote the progression of ankylosing spondylitis (AS) through mechanisms such as interference with the Akt/mTOR signaling cascade and pyroptosis." (PMID 39188714, 2024).
aortic coarctation (1 paper, 2018). "Our study suggested that rats treated with DS after suprarenal abdominal aortic coarctation surgery showed attenuated cardiac fibrosis and apoptosis, and the protective effect may be correlated with the activation of PI3k/Akt/mTOR dependent manner." (PMID 30008784, 2018).
aplastic anemia (1 paper, 2015). Anemia resulting from bone marrow failure (aplastic or hypoplastic bone marrow). "Our data argue against a therapeutic use of mTOR inhibitors to treat aplastic anemia in DKC patients with TERT mutations." (PMID 26546739, 2015).
aspergillosis (1 paper, 2024). Aspergillosis is an infection, growth, or allergic response caused by the Aspergillus fungus. "In the context of aspergillosis, macrophages depend on enhanced glucose metabolism, driven by the activation of mammalian target of rapamycin (mTOR) and hypoxia-inducible factor-1α (HIF-1α), to support their antifungal effector activity." (PMID 38651925, 2024).
astrocytic tumor (1 paper, 2026). A glial tumor of the brain or spinal cord showing astrocytic differentiation. "Altered mTOR signaling in relation to amino acid sensors might represent factors that modify proliferation and treatment responses in astrocytic tumors." (PMID 41865271, 2026).
atrioventricular (AV) block (1 paper, 2022). "Now, the potential proarrhythmic effect of chronic treatment of PI3K/mTOR inhibitor GSK2126458 (omipalisib) was investigated in the atrioventricular (AV) block dog model." (PMID 35990966, 2022).
autoimmune vasculitis (1 paper, 2023). An autoimmune form of vasculitis. "In one such case, targeting mTOR hyperactivity with sirolimus allowed for improved management of the associated autoimmune vasculitis." (PMID 37274825, 2023).
bile duct cancer (1 paper, 2021). "In summary, the results suggested that EMI2 inhibited apoptosis in the bile duct cancer cells and promoted cell cycle progression through the PI3K/Akt/mTOR signaling pathway." (PMID 34933678, 2021).
bone metabolic disorder (1 paper, 2022). "The mechanism of multiple pathways involves the regulation of mitophagy and is especially focused on the regulation of mTOR in bone metabolic disorder." (PMID 35681421, 2022).
brain glioblastoma (1 paper, 2025). A WHO grade IV malignant astrocytic tumor that arises from the brain, usually the cerebral hemispheres. "According to previous studies, brain glioblastoma development and occurrence are also significantly influenced by the P13K/Akt/mTOR signaling pathway." (PMID 40504869, 2025).
brainstem tumors (1 paper, 2023). "We focused on mutations linked to discrete brain regions and key biological pathways altered in DMGs, including mutations specific to thalamic and brainstem tumors and affecting receptor tyrosine kinases; BMP, PI3K/mTOR, and MAPK signaling; the cell cycle; and DNA repair." (PMID 37011011, 2023).
breast NETs (1 paper, 2022). "The most commonly affected oncogenic pathways in the breast NET cases were PI3K/Akt/mTOR, NOTCH and RTK-RAS pathways." (PMID 36085291, 2022). "Nevertheless, according to our analysis, the PI3K/Akt/mTOR pathway, NOTCH pathway and RTK-RAS pathway were the most commonly affected oncogenic pathways in breast NETs." (PMID 36085291, 2022).
bronchial carcinoma (1 paper, 2022). "In bronchial carcinoma cells, treatment with SHI also reduced mTOR expression and phosphorylation." (PMID 35267423, 2022).
capillary leak syndrome (1 paper, 2015). A syndrome characterized by leakage of intravascular fluids into the extravascular space. "For instance, capillary leak syndrome by bortezomib administration and high frequency of grade 1–2 ILD by mammalian target of rapamycin (mTOR) inhibitor are examples of specific ILD features related to molecularly targeted drugs." (PMID 25967287, 2015).
Caroli disease (1 paper, 2012). Caroli disease (CD) is a rare congenital liver disease characterized by non-obstructive cystic dilatations of the intra-hepatic and rarely extra-hepatic bile ducts. "In addition, the activation of the mammalian target of rapamycin (mTOR) pathway has been implicated in the overgrowth of cholangiocytes in Caroli's disease." (PMID 22007315, 2012).
catalepsy (1 paper, 2020). A nervous system disorder characterized by diminished responsiveness and consciousness, and rigidity of the body. "As striatal genetic depletion of mTOR completely abolished the haloperidol-induced catalepsy, we next asked whether pharmacological inhibition of mTOR would produce a similar phenotype." (PMID 33009372, 2020).
central precocious puberty (1 paper, 2024). "The mechanistic target of rapamycin (mTOR) signaling pathway has a significant effect on central precocious puberty (CPP)." (PMID 38516410, 2024).
cerebellar hemangioblastoma (1 paper, 2019). A histologically benign tumor, usually cystic with a vascular mural nodule, that is most often found in the cerebellum though it has been reported at other sites within the neuraxis. "The phospho‐S6 ribosomal protein in the mTOR pathway is a potential target in VHL‐related cerebellum hemangioblastomas." (PMID 31317677, 2019). "Based on our results, mTOR signaling might play an important role in the development of cerebellar hemangioblastoma in patients with VHL disease and may be a target for future research on VHL‐related cerebellum hemangioblastomas." (PMID 31317677, 2019).
cerebral cavernous malformation (1 paper, 2024). A disorder characterized by malformations in the structure of the capillaries in the brain. "As a common vascular abnormality in the central nervous system, cerebral cavernous malformations (CCMs) require the upregulation of the phosphatidylinositol-3-kinase-mTOR pathway and the loss of CCM complex function to grow." (PMID 38461206, 2024).
chloroma (1 paper, 2021). "The backward elimination procedure identified RUNX1T1, MAPK3, PIK3CG, TCF7L1, GRB2, and MTOR as the empirical drivers of the association with chloroma." (PMID 33882829, 2021).
cholesteatoma (1 paper, 2024). A pathologic process characterized by the proliferation of keratinizing squamous epithelium resulting in the accumulation of keratin and cells in the middle ear and/or mastoid. "Expression of LC3, p-Akt, and p-mTOR was also analyzed in post-auricular skin and cholesteatoma samples from 10 patients using immunohistochemistry." (PMID 38391409, 2024). "Notably, this suppressed autophagy in cholesteatoma tissue appears to be linked to LC3 rather than the Akt/mTOR signaling pathway." (PMID 38391409, 2024). "In a recent study addressing this question, paired retroauricular skin (control subject) and cholesteatoma (CholeOM patient) samples from 15 patients, collected during surgery, were analyzed for LC3, phosphorylated Akt (p-Akt), and phosphorylated mTor (p-mTOR) by Western blot analysis." (PMID 38391409, 2024).
choroideremia (1 paper, 2024). Choroideremia (CHM) is an X-linked chorioretinal dystrophy characterized by progressive degeneration of the choroid, retinal pigment epithelium (RPE) and retina. "Torin increased autophagic flux in CHM−/− iPSC-RPE more than control iPSC-RPE cells (3.6-fold vs. 1.2-fold, p < 0.0001), thus supporting the role of mTOR signaling in reducing autophagic flux in choroideremia." (PMID 38920696, 2024).
chronic asthma (1 paper, 2013). An asthma that is characterized by the development of persistent airway inflammation and recurrent attacks of breathlessness and wheezing, which vary in severity and frequency. "Above all, mTOR signaling appears to be implicated in the airway smooth muscle hyperplasia and hypertrophy seen in chronic asthma." (PMID 24312355, 2013).
chronic osteomyelitis (1 paper, 2025). "For instance, while metformin promotes M2 polarization via the AMPK/mTOR pathway, systemic administration may disrupt normal immune surveillance, further complicating pathogen clearance in chronic osteomyelitis." (PMID 40584964, 2025).
complex regional pain syndrome (1 paper, 2015). A chronic pain syndrome characterized by a disproportionate spontaneous or stimulus-induced pain, accompanied by a variably mixed myriad of autonomic and motor disorders including symptoms such as swelling, allodynia, skin blood supply and trophic disturbances. "Chronic treatment of patients with mTOR inhibitors is associated with an increased incidence of pain, including the possible development of complex regional pain syndrome (CRPS)." (PMID 26770837, 2015).